CXCL1 (C-X-C motif chemokine ligand 1)
Diseases named in the same sentence as CXCL1 in open-access papers (continued):
Sharing a sentence is not in itself a finding about the gene and the disease.
tumor (continued). "Similarly, combined expression of Cxcl1 and Ccl2 in 889-S1 tumour cells substantially counteracted the inhibitory effects of USP12 on the TAM infiltration and their PD-L1 expression as well as on CD31+ cell presence." (PMID 34381028, 2021). "Therefore, Cox2 controls Cxcl1 expression, senescence surveillance, and long-term tumor suppression in the context of RIS in vivo." (PMID 33730589, 2021). "Reports have described that stromal and immune cells may produce the chemokine CXCL1, which works in a paracrine manner in the tumor environment through cancer development." (PMID 33707603, 2021). "To explore whether ESCC tumor cell‐secreted CXCL1, upregulated by LAMC1, influences CAF heterogeneity, we performed mRNA‐seq in the following cells: CAF treated with PBS; CAF with recombinant CXCL1 (rCXCL1) treatment; CAF with sh‐vec CM treatment." (PMID 34218518, 2021). "Similarly, co-expression of Cxcl1 and Ccl2 in 889-S1 tumour cells substantially increased tumour incidence and growth in the presence of USP12 overexpression, suggesting the importance of the tumour-extrinsic effects controlled by USP12." (PMID 34381028, 2021). "At the same time, by comparing the expression of CXCL1 between tumor and paracancerous tissues in COAD patients from TCGA cohort, we also observed that the expression of CXCL1 was dysfunctional between tumor and paracancerous tissues, and CXCL1 was significantly up-regulated in tumor tissues." (PMID 34405013, 2021). "CXCL1/2-expressing tumor cells can recruit CD11b+ Gr1+ bone marrow cells and CXCL1/2 expression promotes lung metastasis and may contribute to metastatic niche formation after tumor cell dissemination." (PMID 33466892, 2021). "In addition, we have also identified a set of genes that are regulated in the opposite way by 7SK and FOXJ3/THRA, including four positive regulators in tumor migration (CXCL1, SYDE1, COL5A1, and HIF1A)." (PMID 33868377, 2021). "Notably, administering a CXCR2 (the receptor for CXCL1 and CXCL2) blocking antibody resulted in reduced accumulation of PMN–MDSCs in the colon and subsequently prevented tumor development in inducible models of colitis-associated cancer." (PMID 34065010, 2021). "Repeated doses of colonosphere-derived EVs into tumor-free mice also increased the number of neutrophils present in the bone marrow and circulation, as well as the primary tumor because cells in the colonospheres increased expression of the neutrophil-recruiting chemokines CXCL1 and CXCL2." (PMID 33946403, 2021). "This raised the possibility that tumor-derived CXCL1 attracts macrophages and T cells, which release HB-EGF and might reduce the inhibitory effects of AR37." (PMID 33941851, 2021). "For instance, CXCL1 promotes tumor angiogenesis in ovarian cancer." (PMID 34603309, 2021). "However, in an in vivo model of Lewis lung carcinoma, cycling hypoxia increases the level of CXCL1 in a tumor." (PMID 33467722, 2021). "Notably, full-length F3 induces tumor angiogenesis via inducing the expression of angiogenesis-related factors IL-8, CXCL-1, and VEGF-A." (PMID 34066023, 2021). "Moreover, CXCL1 levels in the urine of BCa patients were higher compared to control subjects but no statistical differences were noted between high and low grade or tumor stages." (PMID 34572939, 2021). "In vivo, knockdown of CXCL1 resulted in the prevention of tumor growth in nude mice." (PMID 33767987, 2021).
tumor (continued). "Additionally, anti-PD-L1 plus anti-TGF-β combination treatment led to upregulation of additional chemokines such as Cxcl1 and Cxcl2 in tumor cells above and beyond those induced by either single treatment alone." (PMID 34030676, 2021). "Colon cancer cells secrete VEGF-A, which stimulates CXCL1 expression in the primary tumour by TAMs." (PMID 33669775, 2021). "Interestingly, tumor exosomal RNAs activate alveolar epithelial toll-like receptor 3 (TLR3) to induce chemokines (CXCL1, CXCL2, CXCL5, and CXCL12) that are critical for neutrophil recruitment and lung pre-metastatic niche formation." (PMID 33101283, 2020). "Tumor cells secrete CXCL1 to recruit MDSCs into the TME in which they suppress T cell infiltration." (PMID 32499786, 2020). "Furthermore, we identify recruitment of immunosuppressive Gr1+ myeloid cells via tumor cell expression of CXCL1, CXCL2, and CXCL8 (CXCR2 ligands) expression, which were substantially reduced with MEKi or CXCR2 blockade." (PMID 32634121, 2020). "It was also reported that CXCL1 could attract CD11b+ Gr1+ myeloid cells into the tumor, resulting in the production of chemokines including S100A8/9 that enhancing tumor growth and metastasis." (PMID 32213179, 2020). "Consequently, tumor self-seeding leads to enhanced angiogenesis, tumor growth, stromal recruitment through seed-derived factors including the chemokine CXCL1, anaplasia, tumor size, and vascularity." (PMID 32264958, 2020). "ELR chemokines include CXCL8, CXCL3, and CXCL1, which promote tumor angiogenesis." (PMID 32462020, 2020). "Moreover, in vivo tumor xenograft mice model demonstrated that CXCL1‐knockdown prolonged the overall survival of tumor‐xenografted mice and increased the sensitivity of GBM." (PMID 32187449, 2020). "CXCL1 autocrine and paracrine networks can also promote tumor invasion and metastasis." (PMID 32079335, 2020). "In addition, the tumor-derived cytokines CXCL1, CCL3, CXCL2, TIMP-1, and TNF-α, which have been implicated in the generation, migration, and activation of MDSCs at the tumor site, were regulated by the modulation of MDSCs." (PMID 33091036, 2020). "Indeed, we demonstrated anti-inflammatory status as evidenced by reduced Ccl2 and Cxcl1 in all the tumor tissues compared to the primary cells." (PMID 32244522, 2020). "In the context of cancer, CXCL-1, IL-8 and IL-6 were known to tune the tumour microenvironment." (PMID 33267794, 2020). "Moreover, in vitro cell viability assays were carried out to explore the effect of CXCL1 knockdown on tumor proliferation of U87 and U251 cells." (PMID 32187449, 2020). "Recent studies have shown that the CXCL1/CXCR2 signaling pathway regulates the inflammatory response; moreover, the pathway causes tumor cell proliferation, angiogenesis, and lymph angiogenesis and promotes tumor invasion and vascular metastasis." (PMID 32190668, 2020). "Furthermore, tumor xenograft experiments were conducted and indicated the positive effect of CXCL1 on CRC proliferation in vivo via JAK-STAT activation as well." (PMID 34079750, 2020). "In addition, further analysis of CXCL1 in samples from TCGA-COAD and TCGA-READ datasets revealed that CXCL1 expression in tumor tissue was significantly elevated relative to that in normal tissue." (PMID 34079750, 2020). "Similarly, fibroblasts when co-cultured with prostate cancer cells produce CXCL1 (which binds to CXCR1 receptor on tumor cells)." (PMID 33414786, 2020). "Furthermore, interaction of cholangiocarcinoma cell-derived EVs with MSCs induces the expression of α-smooth muscle actin, CCL2, CXCL-1, IL-6 in the MSCs which in turn influence the proliferation of tumor cells via enhanced STAT3 phosphorylation." (PMID 32499786, 2020). "Besides, a study demonstrated that the expression of CXCL1 in tumor cells was elevated after paclitaxel and docetaxel treatment." (PMID 31998654, 2019).
tumor (continued). "The PCa metastasis secretome study further suggests CXCL1 functions as a paracrine factor and may play a role in PCa bone metastasis by mediating cross-talk among multiple cell types within the tumor microenvironment." (PMID 31500632, 2019). "Secondly, NLRP12 downregulates hepatocyte-specific expression of cytokines such as IL-6 and TNFα which promote proliferation and tumor growth, and chemokines CXCL1, CXCL2 and CCL2, which enhance inflammatory cell infiltration and thereby augment inflammation in the tumor milieu." (PMID 30990169, 2019). "Moreover, ectopic expression of DACH1 significantly inhibited the expression of CXCL1, Ki67, and cyclin D1 in tumor tissues compared with A549 cells with empty vector." (PMID 31998654, 2019). "Here we questioned whether overexpressed CXCL1 in PCa as well as potentially recruited neutrophil might exert any influence on tumor cells by paracrine cytokine secretion." (PMID 31500632, 2019). "Furthermore, thrombin stimulates tumors to secrete CXCL1 in endothelial cells, which reinforces tumor angiogenesis." (PMID 31788042, 2019). "In a recent publication, we showed that IL-1β secreted by IRISOE TNBC tumor cells within the aggressiveness niche recruited MSCs to the aggressiveness niche and initiated strong bi-directional interactions with them that led to CXCL1 secretion from MSCs." (PMID 31014367, 2019). "Moreover, PP2, a specific SFKs inhibitor mainly targeting Lck/Fyn and displaying anticancer activity, abrogated the migration of CXCL1/LCN2 stimulated tumor cells." (PMID 31500632, 2019). "Taken together, our results provide mechanistic insights into the interaction between PCa cells, stromal cells, and innate immune cells in tumor microenvironment and highlight the role of CXCL1 and LCN2 in a tumor-stroma paracrine axis in promoting cancer-cell aggressiveness." (PMID 31500632, 2019). "Notably, CXCL1 expression was much higher in tumor foci than para-carcinoma tissue (PCT) in the same PCa samples as well as unrelated normal prostate tissues (p < 0.001)." (PMID 31500632, 2019). "We next examined whether CXCL-1 was functionally essential in mediating tumor and stromal cross-talk." (PMID 31500632, 2019). "CXCL1 was regulated by multiple signal pathways and tumor microenvironment." (PMID 31998654, 2019). "In 4T1 cells, shRNA-knockdown of CXCL1 impeded tumor growth and angiogenesis." (PMID 31788042, 2019). "The results showed that the serum of tumor-bearing mice exhibited a substantially increased proportion of mo-MDSCs than that of control mice and the addition of CXCL1 or CXCL2 induced a greater proportion of mo-MDSCs compared to the serum of only tumor-bearing mice." (PMID 31395859, 2019). "Simultaneously, CXCL1 activates the prosurvival Mek/Erk pathway in the tumor cells." (PMID 31101063, 2019). "MSC/fibroblast-derived chemokines, including murine CXCL1 and CXCL2 (counterparts of human CXCL8), CCL2 and CCL5 were associated with recruitment of neutrophils, tumor-associated macrophages and myeloid-derived suppressor cells to TNBC tumors, where they promoted disease course." (PMID 31031757, 2019). "One of the mechanisms by which this circulating neutrophilia and accumulation in tumor develops is likely related to the direct release from tumor cells of cytokines such as CXCL1, CXCL5 and, in particular, IL-8 which is known to be a potent chemoattractant for neutrophils." (PMID 31824850, 2019). "In PDAC, CXCL1 is described as being a part of the NDRG1/Cap43 regulated tumor suppressor pathway." (PMID 31561620, 2019). "The RIP 1/3 promote PDAC oncogenesis and induce the immunosuppressive tumor microenvironment through both the necroptosis-induced CXCL1 and Mincle signaling; whereas, depletion of RIP 1/3, CXCL1, or Mincle protected against PDAC progression and restored anti-tumor immunity in vivo." (PMID 31540286, 2019).
tumor (continued). "The recruitment of TAN is achieved through the release of specific chemokines from the tumor microenvironment—CXCL1, CXCL2; cytokines—INF- γ, TNF-α; growth factors—granulocyte colony stimulating factor (G-CSF) and presence of specific adhesion molecules on the EC surface." (PMID 30680411, 2019). "In explant cultures, tumor CXCL1 concentrations predicted the response to oxaliplatin + curcumin." (PMID 31132111, 2019). "Moreover, CXCL1 overexpression is essential for the obesity-dependent tumor adipose stromal cells recruitment and ultimately promotes PCa progression." (PMID 31500632, 2019). "Furthermore, the differentiation of CXCR2−/− bone marrow progenitor cells into mo-MDSCs was markedly reduced compared with the WT mice in the serum of tumor-bearing mice or tumor-bearing mice supplemented with recombinant CXCL1 or CXCL2." (PMID 31395859, 2019). "Mechanistically, this was linked to an increased RIPK1/RIPK3-dependent protein product of PDA cells (SAP130), which promoted cellular immune suppression by tumour infiltrating macrophages expressing the protein receptor (Mincle) that were themselves recruited in a CXCL1-dependent manner." (PMID 31416294, 2019). "CXCL1 and GM-CSF have been reported to recruit myeloid-derived suppressor cells (MDSCs), a cell type connected to tumor angiogenesis and T cell immunosuppression while IL-8 and IL-6 have been linked to the recruitment of mesenchymal stem cells and neutrophils amongst others." (PMID 30111846, 2018). "The chemokine CXCL1 (GRO-α encoding protein) is the key component of tumor cells in a wide range of normal and pathological conditions, including inflammation, angiogenesis, wound healing, and tumor invasion." (PMID 29667478, 2018). "This outcome suggests that therapy targeting, in part, chemokine receptor pathways including Cxcl1/Cxcr2, may be an effective approach for reducing or preventing the tumor-promoting effect of the inflammatory TME." (PMID 29487713, 2018). "Moreover, the expression of CSC-related transcriptional factors, Nanog, Oct4 and Sox2, were enhanced by CXCL1 in SW620 tumor spheroids." (PMID 30115896, 2018). "Furthermore, MLACs recruited MDSCs via the secretion of CCL2/5 and CXCL1/2/5, thereby enhancing the immunosuppressive tumor microenvironment and promoting TAMs-mediated tumor progression." (PMID 29541408, 2018). "Furthermore, as the tumor cells secrete TGFβ, deletion of TGFβ receptor 2 (Tgfbr2) within the tumor is demonstrated to increase CXCL1/CXCL5 –CXCR2 chemokine and chemokine receptor signaling." (PMID 29966014, 2018). "The subset of genes upregulated in lungs of both tumor free and metastatic Ikkβ-deficient animals comprised Tnfa, Ccl5, Ccl17, Ccl22, Cxcl1 and Csf2, although not all changes reached significance." (PMID 29682184, 2018). "Furthermore, experimental depletion of Uev1 in HCT116 cells reduces CXCL1 expression, and prevents cell invasion and tumor growth in a xenograft mouse model." (PMID 29662619, 2018). "Because CXCL1 knockdown in THP-1 cells did not influence macrophages proliferation and invasion, tumor regression might have been due to subsequent reactions of cancer cells responsive to CXCL1 knockdown in macrophages." (PMID 30158589, 2018). "Since Cxcl1 exhibited the greatest change in expression among all chemokine genes after Plac1 downregulation, mice were treated with a Cxcr2 antagonist to determine if it would affect tumor growth to a similar extent." (PMID 29632317, 2018). "In addition, proteins involved in tumor cells invasion such as CXCL1, CXCL5, and MMP1 were displayed to be expressed and interacted with ICAM-1 and TGFβ2 in the network analysis." (PMID 29966014, 2018). "Similar to observations in hemorrhagic areas of the tumor, the presence of RBCs increased mRNA expression of Cxcl1 (KC), Cxcl2 (MIP-2), and Csf1 (M-CSF), suggesting that the activation of macrophages by heme/iron may trigger recruitment of myeloid cells." (PMID 29167669, 2017).
tumor (continued). "Finally, we defined a tumor-derived TGF-β-triggered CXCL1/2/5- and CXCR2-dependent recruitment of MDSC into the liver." (PMID 28243237, 2017). "On the other hand, the rescue of CXCL1 expression in the PC-3 tumors blunted the WCE-mediated immune modulation by increasing Ly6G+ MDSCs infiltration thus reversing the detrimental effect of WCE on the tumor growth." (PMID 29142311, 2017). "The authors concluded that the ERO-α enzyme contributes to the suppression of anti-tumor immunity by regulating G-CSF cytokines and CXCL1/2 via facilitating proteins folding, suggesting that inhibition of the ERO-α enzyme may difficult cancer progression." (PMID 28775257, 2017). "Taken together suggest that whether secreted by IRISOE cells or MSCs exposed to IRISOE CM, CXCL1 signaling is unidirectional from MSCs to IRISOE tumor cells." (PMID 29262555, 2017). "Furthermore, PGE2 can promote tumor progression by inducing the expression of C-X-C motif ligand 1 (CXCL1), a proangiogenic chemokine that can induce microvascular endothelial cell migration and tube formation to promote tumor growth as well as invasion." (PMID 28852270, 2017). "However, there was a significant effect of tumor cell type on IL-1β (H = 29.44, p < 0.0001), IL-6 (F2, 37 = 13.68, p < 0.0001), TNFα (F2, 38 = 26.73, p < 0.0001), and CXCL1 (H = 10.86, p < 0.005)." (PMID 28811490, 2017). "Our study investigated whether attenuation of DNA damage repair by 10 μM ATM kinase inhibitor Ku55933 could reverse CXCL1-conferred tumor radioresistance." (PMID 28518141, 2017). "As CAF-secreted CXCL1 was discovered as an important radiosensitizing target in vitro and in vivo, our study further explored its clinical significance by analysis of patients’ plasma and tumor tissues." (PMID 28518141, 2017). "Our working hypothesis is that within the aggressiveness niche, IL-1β secreted by metabolically stressed, hypoxic and inflamed IRISOE TNBC tumor cells recruits MSCs to the niche (step 1), and activates them to secrete CXCL1 (step 2)." (PMID 29262555, 2017). "By ELISA, the concentration of CXCL1 was found to be significantly higher in plasma samples of ESCC patients (n=35) compared with that in healthy controls (n=29), suggesting CXCL1 may serve as a potential tumor biomarker of ESCC patients (P=0.04207)." (PMID 28518141, 2017). "Furthermore, we elucidated that knockdown TGF-β from tumor cells significantly reduced the expression of chemokines (CXCL1, 2, and 5) in liver tissues, resulting in much less influx of MDSCs into the liver." (PMID 28243237, 2017). "Notably, CXCL-1 was found to be secreted from tumor stromal cells and affect cancer progression via a paracrine signaling." (PMID 29109519, 2017). "By contrast, PD-L1-deficient tumours exhibited a different array of T-cell chemoattractants (e.g., CX3CL1), and an increase in general inflammatory cytokines, especially those associated with neutrophil/granulocytic MDSC infiltration, for example, CXCL1/3/5." (PMID 28220772, 2017). "Our study further explored how CAF-secreted CXCL1 conferred tumor radioresistance." (PMID 28518141, 2017). "Neutrophils, which have potentials in promoting tumor growth and metastasis, were recruited by CXCL1/CXCR2 axis after liver IR injury and took part in facilitating tumor recurrence as proven by neutrophil-depletion-mediated protection against tumor cells invading." (PMID 29179487, 2017). "Indeed, estrogen induces neutrophil expression of a plethora of genes encoding protumoral cytokines/chemokines(e.g. CXCL1, CXCL2, S100A8, S100A9), matrix metalloproteinases(MMP3, MMP9) and COX-2 that are all known to promote tumor growth and metastasis." (PMID 28429725, 2017). "Cumulatively, and combined with previous reports from our laboratory, these correlative data suggest that the CXCL1/CXCR2 chemokine signaling axis may be a principal driver of gMDSC recruitment into the MOC tumor microenvironment." (PMID 28915554, 2017).